CD27 (CD27 molecule)
Diseases named in the same sentence as CD27 in open-access papers (continued):
Sharing a sentence is not in itself a finding about the gene and the disease.
tumor (continued). "Despite its potential, REM has been shown to greatly reduce CD28 and CD27 expression on the expanded TIL, and this is associated with reduced persistence and hence limited anti-tumor activity of the infused TIL." (PMID 23402380, 2013). "To this end, we investigated the expression of CD11b and CD27 on NK cells isolated from primary human NSCLC tumour specimens and peripheral blood from the same patients as well as peripheral blood from healthy control subjects." (PMID 23565296, 2013). "Long telomere length and high CD27 expression are markers of less differentiated cells which appear to correlate with persistence and anti-tumor response." (PMID 21234353, 2010). "Analysis of MC38 tumor-bearing mice treated with the Bpmel-SIY-OVAII cell adjuvant revealed a sustained increase in the proportion of CD27− CX3CR1+ and CD62L− CD44+ effector CD8+ T cells in the DLN as well as more significant infiltration of CD8+ T cells in the tumor site." (PMID 41348109, 2026). "Notably, exhausted CD27+ T cells concentrated in tumor core regions, while effector populations distributed peripherally." (PMID 42294500, 2026). "Furthermore, CD27 signaling increases regulatory T cell (Treg cell)-infiltration promoting tumor growth." (PMID 40205178, 2025). "Given that tissue-level expression data of prognostic biomarkers are particularly valuable in this aggressive cancer, our research gives a solid basis for validation and experimental studies in the future to underpin the role of the CD70/CD27 axis in SCLC tumor immunology." (PMID 40205178, 2025). "Overexpression of CD27 within CD4+ T cells may suppress anti‐tumor immunity by enhancing regulatory T cell (Treg) function." (PMID 41057994, 2025). "We hypothesize that elevated CD27 levels may contribute to the development of tumor cells with a less aggressive phenotype or enhance immune system-mediated tumor control." (PMID 40647640, 2025). "Moreover, memory subsets represented the predominant differentiation stages of γδT cells, with γδTCM (CD27+) being significantly increased in tumor tissue and γδTEM (CD27-) dominating in ascites." (PMID 41221283, 2025). "The incorporation of 4-1BB or CD27 costimulatory domains significantly enhanced the anti-tumor response by promoting T-cell persistence and functionality, leading to a substantial reduction in tumor growth." (PMID 39941106, 2025). "Starting with T cell stimulating receptors, percentages of CD27 expression were highest on blood-circulating CD4+ T cells (87.52 ± 2.57% of CD4+ T cells) and CD8+ T cells (60.59 ± 4.98% of CD8+ T cells) followed by ascites samples and tumor tissues having least CD27+ T cell proportions." (PMID 41221283, 2025). "CD27 co-stimulation is also crucial for boosting CAR-T cell anti-tumor efficacy." (PMID 40236693, 2025). "Tumor cells regulate CD27 expression in the TME by expressing CD70, which promotes immune escape." (PMID 40205178, 2025). "The analysis showed that tumor-infiltrating CD27+Ly6C− γδ T cells increased expression of each marker when compared to CD27+Ly6C− γδ T cells in the spleen, LN, or lung, indicating that CD27+Ly6C− γδ T cells are modified by tumors." (PMID 38816652, 2024). "In addition, global CD27 KO mice showed a significantly higher burden of metastatic tumor nests in the lungs compared to WT controls." (PMID 39105866, 2024). "In addition to their endogenous anti-tumor role, CD27+ IFNγ-producing γδ T cells control tumor growth after ex vivo expansion and adoptive cell transfer into tumor-bearing mice, mirroring the outcomes of experiments using human Vγ9Vδ2+ or Vδ1+ cells." (PMID 38816652, 2024). "Furthermore, CD27 expression in plasma cells is intricately tied to tumor burden, treatment response, and overall prognosis in MM patients." (PMID 38504180, 2024). "Next, we looked at how age affected the expression of CD27 in individuals with each type of tumor." (PMID 38169519, 2024).
tumor (continued). "We investigated the frequency and phenotype of CD27+Ly6C+ γδ T cells in tumor-bearing mice to determine whether tumor-derived factors influence these cells." (PMID 38816652, 2024). "CD27 showed significantly high expression in 21 cancers, the high expression and good prognosis of CD27 in these cancers prove the theory that CD27 acts as a co-stimulatory immune checkpoint in tumor cell immunity." (PMID 38169519, 2024). "This suggests that the upregulation of CD27 can promote tumor-specific cellular immunity." (PMID 38169519, 2024). "However, CD27+Ly6C− and CD27+Ly6C+ γδ T cells within the tumor microenvironment expressed the same levels of CD160, NKG2A, NKp46, and CD44, with NKG2A expression in KP tumors being an exception." (PMID 38816652, 2024). "A significant increase in the percentage of positive mature NK cells (CD27+CD11b+) was found in both groups of mice treated with Ox-RtH and Ox-HaH compared with untreated tumor-bearing animals, while a significant decrease was measured in activated CD8+ T cells in both groups (middle)." (PMID 39452870, 2024). "Therefore, it can be inferred that CD27 can directly inhibit tumor progression by downregulating the relevant pathway." (PMID 38169519, 2024). "In our model, tumor inoculation in single cell suspension may favor infiltration of CD27-expressing effector lymphocytes that protect against tumor growth and metastasis in a CD27-dependent fashion." (PMID 39105866, 2024). "Only IFNγ remained higher on CD27+Ly6C+ γδ T cells in both tumor models." (PMID 38816652, 2024). "Combination therapies with agonistic anti-CD27 agents or pegfilgrastim may also promote better myeloid cell recruitment and anti-tumor activity." (PMID 39449327, 2024). "Adding CD3xTRP1 treatment resulted in the emergence of a population of highly activated OT-1 T cells in the tumor, reflected by a significant upregulation of intracellular GzmB expression, and high expression of multiple activation markers, such as 4-1BB, CD27, NKG2A, PD-1 and Tim3." (PMID 38167722, 2024). "Therefore, we can infer that the CD27 is initiated in tumor progression and have a positive inhibitory effect on the development of tumors." (PMID 38169519, 2024). "Therapy with Ox-RtH or Ox-HaH resulted in the generation of enhanced specific immune response (increased levels of tumor-infiltrated mature NK cells (CD27+CD11b+) in sensitized groups and of macrophages in the intensively immunized animals) and tumor suppression." (PMID 39452870, 2024). "Importantly, our research found that GCP greatly increased the proportion of γδT cells in the spleen and tumor, and the infiltrating γδT cells in the tumor were CD27+ type." (PMID 38604998, 2024). "However, recent studies with diverse tumor and transplant models have described more complicated or even conflicting roles for CD27 in T cell-mediated immune responses." (PMID 39105866, 2024). "This can reflect the positive effect of the CD27 on tumor antigen presentation." (PMID 38169519, 2024). "Specifically, tumor fragment implantation may have attracted immune profiles in which CD27-expressing Treg cells play a major role in dampening antitumor response." (PMID 39105866, 2024). "Moreover, CD27 is expressed on tumor-infiltrating lymphocytes (TILs) and can transmit signals to T and NK cells across a variety of tumors." (PMID 38909269, 2024). "Additionally, the relationship between immunological check-point markers and CD27 expression suggests that CD27 has a function in controlling tumor immunology in malignancies, particularly in BRCA, PRAD, LUAD, BLCA, and OV." (PMID 38169519, 2024). "Similarly, the frequency of tumour-infiltrating CD3+CD8+CD27+ T cells were significantly lower post-CROSS chemoradiation compared with the treatment-naïve setting (16.8 ± 3.1 vs. 4.64 ± 1.9%, p = 0.03)." (PMID 35986757, 2023).
tumor (continued). "Furthermore, lymphatic invasion—a clinical tumor characteristic—of immune genes, including CD27, CD48, and CD28, as well as infiltration of CD8+ T cells exhibited a positive and substantial connection with LCK expression (in terms of immune cells)." (PMID 37773310, 2023). "On the other hand, in-vivo CD27 engagement by CD70 on B-cells has shown to augment primary CD8+T-cell responses and tumor rejection even in poorly immunogenic tumor models, as CD27 stimulation can boost antigen-specific CD8+T-cell expansion and concomitantly improve per-cell cytotoxic functionality." (PMID 37345056, 2023). "Similarly, we found that patients with PR had lower levels of CD27 in the tumor compartment relative to those with PD." (PMID 37153589, 2023). "Moving one step forward, adoptively transferred CD70-expressing immature DCs could prime CD8+T-cells, by CD27, to become tumor-eradicating cytolytic effectors and memory cells with a capacity for robust secondary expansion, independently of CD4+T-helpers." (PMID 37345056, 2023). "Moreover, high CD40 expression in tumor regions (HR= 0.27, p-adjusted= 0.035), and high CD27 expression in the stroma (HR= 0.2, p-adjusted=0.032) were associated with better survival outcomes." (PMID 37153589, 2023). "ACM derived from OGJ patients with early-stage tumours and late-stage tumours significantly increased the expression of CD27 on the surface of CD8+ T cells compared with untreated cells (untrx: 41.47 ± 2.7 vs. early-stage: 64.29 ± 4.8%, p = 0.008 and late-stage: 60.75 ± 6.7%, p = 0.01)." (PMID 36790524, 2023). "Moreover, the Fc-silent format of CD27xEGFR enables tumor-localized binding and crosslinking of CD27 only at EGFR+ tumor sites, potentially enhancing its specificity and safety profile." (PMID 37545491, 2023). "Although no upstream factors were predicted for CD27, the results identified a subset of miRNAs and transcription factors that are associated with tumor proliferation, invasion, and immune regulation." (PMID 37766321, 2023). "CD27 agonists could therefore be used to bolster cellular vaccines and anti-tumour immune responses." (PMID 37965342, 2023). "However, CDX-527 relied on both PD-L1 expression and FcR interactions for CD27 crosslinking and activation, potentially unleashing strong on-target but off-tumor activity." (PMID 37545491, 2023). "Coexpression of multiple predictive markers within the same immune subset suggests that key immune populations (e.g., PD-1+CD27+ T cells or HLA-DRhiCD44+ MDMs) may be critical drivers of immunity within the periventricular tumor microenvironment." (PMID 37192001, 2023). "In addition to CD27 being expressed in cytotoxic and exhausted TILs, CD27 mRNA expression was also detected in tumor infiltrating regulatory T cells (Tregs), suggesting possible unwanted co-stimulatory effects on Tregs by CD27xEGFR." (PMID 37545491, 2023). "Moreover, since DCs play an important role in delivering help signals from CD4+ T cells, DC‐based vaccines and the CD27 agonism have recently been exploited to inhibit tumor growth." (PMID 37829505, 2023). "Cancer-derived CD8+ T cells from patients with head and neck cancer when co-cultured with tumor-derived EVs has been shown to induce the loss of CD27 expression in CD8+ T-cell and thus resulting in their change from the anti-tumor phenotype towards a more potent tumor suppressor phenotype." (PMID 37760975, 2023). "Notably, TILs from various cancer types express the co-stimulatory Tumor Necrosis Factor receptor CD27, making it a potential target for co-stimulation and re-activation of tumor-infiltrated and tumor-reactive T cells." (PMID 37545491, 2023). "Varlilumab has a dual role as a costimulation agonist and cytotoxic agent and could potentially enhance T cell responses as well as ADCC towards CD27+ tumor cells." (PMID 37575254, 2023).
tumor (continued). "Similarly, the percentages of tumour-infiltrating CD3+CD27+ cells were significantly lower post-FLOT chemotherapy compared to the treatment-naïve setting (16.1 ± 2.7 vs. 5.41 ± 2.6%, p = 0.01)." (PMID 35986757, 2023). "We also observed that responders had increased percentages of splenic KLRG1+ mature NK cells and tumor-infiltrating CD11b-/CD27- immature NK cells, and decreased percentages of tumor-infiltrating CD11b+/CD27-activated NK cells two weeks after treatment initiation." (PMID 37446056, 2023). "Ιn the malignant setting, a CD27-mediated signal can, strikingly, overrule anti-tumor immunity." (PMID 37345056, 2023). "Future studies, namely those including more recent standards of care such as anti-CD38 monoclonal antibodies, will determine the extent to which the CD27−:CD27+ T cell ratio is a useful maker of tumor specificity and response to lenalidomide-based combinations in MM." (PMID 37730678, 2023). "In addition, when we compared protein biomarker expression between tumor and stromal compartments, we found that CD27 had a higher expression level in the stromal margins of patient responders." (PMID 37153589, 2023). "CD27 (TNFRSF7) is another attractive candidate target to improve tumor immune response." (PMID 37575254, 2023). "In T cells, CD27 co-stimulation is known to augment survival and anti-tumor activity." (PMID 37287982, 2023). "Based on the data presented here, CD27xEGFR may provide tumor-localized binding and crosslinking of CD27 on T cells for EGFR+ carcinomas." (PMID 37545491, 2023). "In this study, we found CD27 to be correlated with tumor grade." (PMID 36458007, 2022). "Moreover, the strong correlation between CD79A and risk score, B cells, T cells, TIGIT, BTLA, CD27, and TNFRSF17 revealed the crucial role of CD79A in regulating the tumor microenvironment (TME) in LUAD patients." (PMID 35295857, 2022). "In addition, in HCC, CD27+ expressing Bregs has also been reported to suppress T cell anti-tumor immunity and promote tumor progression through IL-10 secretion and PD-1 expression." (PMID 36618354, 2022). "In addition, the high glucose environment induced the protein level of CD27 and other molecules in CD8+T cells to increase, which restored the anti-tumor effect of CD8+T cells by increasing CD27 transcription." (PMID 36601120, 2022). "Our results here underpin their notion that CD27 expression on Tregs supports tumor growth." (PMID 34423375, 2022). "However, combined PD-1 blockade and DT injection resulted in a substantial increase in tumor infiltrating CD8+ T cells underlining the synergistic effect of combinatorial PD-1 signaling blockade and CD27 deficiency on Tregs." (PMID 34423375, 2022). "Both the ligand, CD70, and its receptor, CD27, are independently expressed in tumor tissue." (PMID 36180422, 2022). "While in a pro-inflammatory environment, such as secondary lymph nodes, survival of effector T cells was enhanced upon CD27 signaling, increased survival of intratumoral Tregs was observed upon CD27 signaling in the context of a chronically inflamed and well-established tumor." (PMID 34991665, 2022). "To get mechanistic insights into the role of Treg-derived CD27 with combinatorial PD-1 signaling blockade on CD8+ T cell mediated antitumor immunity, we analyzed numbers and effector functions of tumor infiltrating CD8+ T cells in MC38-bearing FoxP3.Luci-DTR5 + CD27 − / − mixed chimeric mice." (PMID 34423375, 2022). "Using the mixed bone chimeric model described here, that allows the ablation of CD27 expressing T cells at a defined point in time allowed us to study the involvement of Treg-expressed CD27 in suppression of immunity to an already established and growing tumor." (PMID 34423375, 2022). "We show that CD27 expression on regulatory T cells is critical for the induction of peripheral CD8 T cell tolerance in the immunological steady state but also limits anti-tumor immunity." (PMID 34423375, 2022).
tumor (continued). "Consistent with the impaired induction of peripheral CD8+ T cell tolerance we had observed in the DIETER model, we found synergistic tumor control upon abrogation of CD27 expression in the Treg compartment and PD-1 blockade to be entirely dependent on CD8+ T cells." (PMID 34423375, 2022). "Here, we have investigated whether the CD70/CD27 axis is also involved in Treg-mediated suppression of anti-tumor immunity." (PMID 34423375, 2022). "Finally, the main variable, CD27 expression, showed a significant correlation with the tumor grade, perineural invasion, chemotherapy, and the HPV status." (PMID 36458007, 2022). "Thus, the selection of a sufficiently agonistic CD27 mAb is clearly critical for effective tumour control." (PMID 35288635, 2022). "These included key genes associated with cytotoxic anti-tumor T cell responses (GZMA, GZMB, PRF1), co-stimulation of T cells (CD27, CD28, ICOS), and genes associated with other immune processes, including Type I IFN response (TNF, TNFSF10), as well as T cell exhaustion (CTLA4)." (PMID 36698398, 2022). "Given the impact of Treg-derived CD27 on tumor growth, we questioned whether PD-1 blockade and abrogation of CD27 in the Treg compartment at the same time might have synergistic effects on antitumor immunity." (PMID 34423375, 2022). "CD27-targeted depletion led to a greater expansion of transferred T cells compared to C/F conditioning and resulted in longer median survival and more cures than C/F conditioning in the E.G7 tumor model receiving OT-I cell therapy." (PMID 34028568, 2022). "Therefore, we analyzed the mRNA expression of several immune cell markers (Cd4, Cd8, Klrb1c, CD27, and Adgre1) within the E0771 tumor tissues from WT and Bgn KO mice." (PMID 33966638, 2021). "In addition, the correlation of the CD70-positivity of tumor cells and CD27-positive TIL on survival was analyzed." (PMID 35145909, 2021). "CD27, a marker involved in T memory cell development and increased cytotoxicity in lymphocytes, was only upregulated with the vIL-2 virus, indicating an additional advantage in the context of long term anti-tumor response." (PMID 34084172, 2021). "Interestingly, increased levels of CD27 in the tumor were detected in KV-treated mice when compared to KK-treated mice, the latter displaying higher CD27 levels compared to controls." (PMID 34885215, 2021). "Moreover, CD27-based CAR T cells promoted long-term anti-tumor activity in vivo by upregulation of the anti-apoptotic protein Bcl-XL." (PMID 35117999, 2021). "The loss of CD27 is also associated with CAR-T cell tonic signaling, which is another well-known phenomenon that contributes to CAR-T cell dysfunction and the loss of in vivo persistence and tumor-clearing ability." (PMID 34298748, 2021). "Moreover, varlilumab, which is anti-human CD27 mAb is in clinical examination phase I or II at the present moment, was able to be synergized with PD-1 blockade in increasing anti-tumor immunity among those mice expressing human CD27." (PMID 34267616, 2021). "CD27 signalling has been found to be necessary to generate robust cytotoxic T cells, so CD27 agonists might further improve anti-PD-1 or CTLA-4 immunotherapy in cases where tumour-specific T cells are suboptimal." (PMID 33262520, 2021). "Moreover, it was demonstrated that CD70 plays a crucial role in evoking immune surveillance by recruiting CD27+ regulatory T-cells (Treg) to the tumor site." (PMID 34200100, 2021). "In turn this may prevent the conversion of NK cell phenotype towards a CD27+ cytokine producing profile, which we propose is detrimental for anti-tumour immunity in OAC, and facilitate the maintenance of the cytotoxic CD27- NK cell population." (PMID 35008227, 2021). "This trend suggests that CD70 expressed in tumor tissue represses anti-tumor immunity via CD27." (PMID 35145909, 2021). "Therefore, we investigated the antitumor activity of the surrogate BsAb in SCID mice transplanted with Raji tumor cells that express high levels of CD27." (PMID 32451681, 2020).